EDN1 (endothelin 1)
Diseases named in the same sentence as EDN1 in open-access papers (continued):
Sharing a sentence is not in itself a finding about the gene and the disease.
cardiac hypertrophy (continued). "Functionally, CCOs recapitulated clinical cardiac hypertrophy by exhibiting thickened chamber walls, reduced fractional shortening, and increased myofibrillar disarray upon treatment with EDN1." (PMID 36544188, 2022). "They investigated the effects of CNP on cultured cardiac myocyte hypertrophy and the interaction between CNP and endothelin-1 (ET-1), which is a representative stimulator of cardiac hypertrophy." (PMID 35741432, 2022). "Endothelin-1 (EDN1) known to induce oxidative stress in cardiomyocytes was used to induce cardiac hypertrophy in CCOs in vitro." (PMID 36544188, 2022). "G protein-coupled receptor-mediated signaling: It is well established that endothelin-1 (ET-1), Ang II, and catecholamines are important inducers of cardiac hypertrophy and chronic heart failure." (PMID 35461308, 2022). "Oxidative stress is a key contributing factor in the development of cardiac hypertrophy, which can be induced by angiotensin II, endothelin-1 as well as catecholamines." (PMID 33479375, 2021). "Referring to our earlier discussion about the role of GPCR pathway in mediating the pathological cardiac hypertrophy, we found that the significant high levels of AT-1 and endothelin-1 appear, for the first glance, conflicting with the literature data." (PMID 34055008, 2021). "The nucleoside counteracts the activity of many neurohumoral factors involved in cardiac hypertrophy, namely endothelin-1, renin-angiotensin-aldosterone system and TNF-α, and noradrenaline release from sympathetic nerves." (PMID 34489711, 2021). "Increased endothelin-1 expression resulted in vasoconstriction and elevated blood pressure, thereby contributing to angiotensin II-induced cardiac hypertrophy." (PMID 32070413, 2020). "ERK1/2 inhibition prevented endothelin-1-induced cardiac hypertrophy in cardiomyocytes from spontaneously hypertensive rats and WKY rats." (PMID 32831633, 2020). "Cardiac hypertrophy cell culture models can be elicited by stimulating cells with agents such as endothelin-1 (ET-1) or angiotensin II (Ang II)." (PMID 31717562, 2019). "Angiotensin II, endothelin-1 and α-adrenergic receptor agonists induce cardiac hypertrophy through G-protein coupled receptors, especially Gαq." (PMID 28487655, 2017). "G-protein coupled receptor (GPCR) agonists, such as phenylephrine, angiotensin II and endothelin-1 are well-known inducers of cardiac hypertrophy." (PMID 29221204, 2017). "Neuroendocrine signals mediated by angiotensin II (Ang II) and endothelin-1 (ET-1) induce cardiac hypertrophy by activating many intracellular signaling cascades." (PMID 27722168, 2016). "Earlier studies did also show that AhR-/- mice had cardiac hypertrophy, blood pressure overload and elevated levels of the proteins endothelin 1 (ET-1), angiotensin-2, β-myosin heavy chain and atrial natriuretic factor." (PMID 27243009, 2016). "In particular, our data show that the involvement of endothelin-1 pathway in T4-induced cardiac hypertrophy/dysfunction seems to be model-dependent and should be carefully interpreted." (PMID 27082116, 2016). "In particular, our data show that the involvement of endothelin-1 pathway in thyroxine-induced cardiac hypertrophy/dysfunction seems to be model-dependent and should be carefully interpreted." (PMID 27082116, 2016). "The signaling cascades of the mitogen activated protein kinase (MAPK) family, calcineurin/NFATc4, and PI3K/Akt/GSK3, are believed to participate in endothelin-1 (ET-1)-induced cardiac hypertrophy." (PMID 26056815, 2015). "N-Acetylcysteine (NAC) can enhance the SOD activity, so the aim of this study is to highlight theinhibitory role of NAC against endothelin-1 (ET-1)-induced cardiac hypertrophy." (PMID 26199914, 2015). "Up-regulation of NGF production by cardiomyocytes was observed in cardiac hypertrophy and upon endothelin-1 treatment." (PMID 24244423, 2013). "This process is involved in Ang II and Endothelin-1 (ET-1) -induced positive inotropic effects and cardiac hypertrophy." (PMID 23116057, 2013).
cardiac hypertrophy (continued). "This critical role of the ERK pathway in the development of cardiac hypertrophy (in response to endothelin-1) was also confirmed by the in vitro abrogation of cardiomyocyte hypertrophy in the presence of the pharmacological inhibitor of ERKs." (PMID 23365487, 2013). "In vitro models of cardiac hypertrophy have been developed to overcome some of these limitations, e.g. neonatal rat cardiomyocytes stimulated by α-adrenergic agonists or endothelin-1, or, when cultured on silicone membranes, by phasic or tonic stretch." (PMID 23099820, 2012). "Endothelin-1 (ET-1) is a major growth factor secreted from endothelial cells that contributes to cardiac hypertrophy and fibrosis." (PMID 21941677, 2011). "Moreover, AngII promotes recruitment of SET1, a histone H3K4 trimethyltransferase, to the endothelin-1 promoter, and enhanced endothelin-1 expression contributes to persistent arterial hypertension and leads to organ damage, such as cardiac hypertrophy." (PMID 41178713, 2025). "This study raised questions about whether enhanced past cardiac expression of FGF23 mediated pathological cardiac hypertrophy through the stimulation of pro-hypertrophic factors such as endothelin 1 (ET1)." (PMID 38846254, 2024). "In addition, the HMT SET1 is activated by angiotensin II stimulation and recruited to the promoter of endothelin-1(a potent vasoconstrictor) to initiate the transcription of endothelin-1 and promote pathological myocardial hypertrophy." (PMID 38584203, 2024). "In addition to hemodynamic overload, endothelin-1 induces cardiac hypertrophy upon binding with ETA receptors and the stimulation of the PLC-mediated signal transduction pathway." (PMID 38786079, 2024). "Similarly, big endothelin-1 (big ET-1), the biologically inactive precursor of endothelin-1, exerts significant effects by reducing cardiac output, promoting myocardial hypertrophy, and stimulating collagen synthesis in cardiac fibroblasts." (PMID 39772209, 2024). "Plenty of evidence has demonstrated that a number of GEFs can be activated by hypertrophic stimuli (PE, Ang II, endothelin-1, Stretch and others) through GPCRs, receptor tyrosine kinases, and other membrane receptors to activate Rac1 and eventually lead to cardiac hypertrophy." (PMID 37524688, 2023). "Furthermore, using lower alcohol concentration in our protocol, the Edn1 mRNA expression remained unchanged after PAEThe renin-angiotensin-aldosterone system (RAAS) contribution to cardiac hypertrophy is widely evidenced." (PMID 36829814, 2023). "Of note, MA Rage−/− mice evidence a transcriptional drift of genes related to the regulation of cardiac cell growth and hypertrophy (Cluster 2B): some of them are positive regulators of cardiac hypertrophy, such as Edn1, while others, such as Ifngr2-Naftcs, mediate antihypertrophic effects." (PMID 36232442, 2022). "Finally, to demonstrate functional utility of the CCO model, EDN1 was used as a cardiac hypertrophy (CH) inducer." (PMID 36544188, 2022). "Moreover, angiotensin II stimulates endothelin-1 (ET-1), which induces cardiac hypertrophy and fibrosis." (PMID 34093852, 2021). "Both in the rat model of cardiac hypertrophy induced by transverse aorta constriction and in hypertrophic cardiomyocyte models treated with different inducing reagents endothelin-1 or phenylephrine, the expression of miR-223-3p in myocardium and cardiomyocytes were downregulated." (PMID 33553260, 2020). "Endothelin-1 signaling promotes cardiac hypertrophy through c-fos-dependent pathways." (PMID 32961896, 2020). "PPAR-α agonists can block cardiac hypertrophy induced by endothelin-1." (PMID 28127304, 2017). "Notably, endothelin-1 treatment which induces cardiac hypertrophy, reduced levels of miR-590-5p and miR-590-3p in human IPSC-CMs." (PMID 27196440, 2016). "Endothelin-1 (ET-1) is also involved in cardiac hypertrophy induced by aging." (PMID 26758611, 2016).
cardiac hypertrophy (continued). "For example, a recent GWAS found evidence for enrichment of risk SNPS in the following pathways: corticotropin-releasing hormone signaling, cardiac β-adrenergic signaling, phospholipase C signaling, glutamate receptor signaling, endothelin 1 signaling, and cardiac hypertrophy signaling." (PMID 25202283, 2014). "Objective(s): The role of the Apoptosis repressor with caspase recruitment domain (ARC) in apoptosis and in certain hypertrophic responses has been previously investigated, but its regulation of Endothelin-1 induced cardiac hypertrophy remains unknown." (PMID 24106598, 2013). "However, idarubicin and daunorubicin displayed higher activation Z-scores compared to doxorubicin and epirubicin for many canonical pathways including ROS, calcium signaling, necroptosis, cardiac hypertrophy, and cardiac repair (apelin, ErbB, and endothelin-1 signaling)." (PMID 33719006, 2021). "Angiotensin II (Ang II), endothelin-1 (ET-1), and insulin-like growth factor-1 (IGF-1) are some of the known neurohumoral factors that can induce cardiac hypertrophy via receptor tyrosine kinases or G-protein-coupled receptors such as Gαq." (PMID 38612393, 2024). "The levels of phosphorylated cofilin-2 are increased in myocardial hypertrophy through the activation of LIM-kinase (LIMK) by ROCK, which is induced by multiple neurohumoral factors, such as angiotensin II, endothelin 1 and leptin." (PMID 36428995, 2022). "Adrenergic activation, catecholamines, angiontensin II (AngII), endothelin 1 (ET-1), and insulin-like growth factor-1 (IGF-1) are well-known neurohumoral factors related to the development of cardiac hypertrophy." (PMID 35721030, 2022). "Overload pressure, oxidative stress and tissue injury, as well as the influence of neurohormonal and inflammatory mediators, like AngII, endothelin-1, catecholamines, growth factors and TNF-α, promote ventricular hypertrophy." (PMID 34489711, 2021). "Endothelin-1 is a strong vasoconstrictor peptide hormone and stimulator of RAS, which is widely used to induce cardiac hypertrophy." (PMID 24877123, 2014). "Cardiac hypertrophy can be induced by treating ventricular myocytes with a wide variety of stimuli, ranging from GPCR agonists like endothelin-1 (ET1) and PE to receptor tyrosine kinase agonists such as epidermal growth factor (EGF)." (PMID 17726532, 2007). "Studies have indicated that EDN1 can inhibit fibroblast apoptosis by activating the PI3K/AKT pathway, and that restraint of the EDN1-induced PI3K/AKT pathway can further alleviate cardiac hypertrophy." (PMID 39863867, 2025). "P300 overexpression in mouse cardiomyocytes stimulates the expression of the GATA4-dependent genes related to cardiac hypertrophy, including natriuretic peptide precursor A(Nppa, mediating the translation of ANP), prepro-endothelin-1(ET-1), and β-myosin heavy chain (Myh7)." (PMID 35958418, 2022). "For example, endothelin 1 induces inositol-1,4,5-trisphosphate receptor (IP3R)-mediated local nuclear Ca2+ release, which in turn activates nuclear CaMKII and affects downstream gene transcription during cardiac hypertrophy." (PMID 36082183, 2022). "We analyzed miRNA-sequencing data (GSE60292) from human IPSC-CMs with/without endothelin-1 treatment (which induces cardiac hypertrophy)." (PMID 27196440, 2016). "For this purpose, the hiPS-CMs were transfected either with Scr siRNAs or with siRNAs of FTO demethylase, and their hypertrophic response were investigated in the presence or absence of the peptide hormone, Endothelin-1 (ET-1), a well-known mediator of cardiac hypertrophy." (PMID 41327199, 2025). "Interestingly, induction of hypertrophy by endothelin-1 treatment significantly reduced levels of miR-590-5p and miR-590-3p in IPSC-CMs (p-value < 0.003 and < 0.002, respectively), suggesting a possible role for miR-590 in cardiac hypertrophy." (PMID 27196440, 2016).
heart failure (128 papers, 2009 to 2026). Inability of the heart to pump blood at an adequate rate to meet tissue metabolic requirements. "In humans, elevated plasma endothelin-1 correlates with the severity of PH and is associated with poor prognosis in heart failure patients." (PMID 37373119, 2023). "Early animal studies suggested an association between endothelin-1 and the development and progression of heart failure." (PMID 37373119, 2023). "Circulating big-endothelin-1, a precursor to ET-1, was recently shown to be associated with all-cause mortality and heart failure progression in HCM." (PMID 37965580, 2023). "In heart failure, plasma levels of both endothelin-1 and large endothelin-1 are elevated and are linked to pulmonary artery pressure, disease severity, and death." (PMID 36264449, 2022). "In streptozotocin-induced diabetic mice, ECs undergo EndMT and begin to express the fibroblast marker endothelin-1 (ET-1) which itself promotes cardiac fibrosis and heart failure via EndMT-associated fibroblast accumulation." (PMID 33767633, 2021). "In fact, modifications in edn1 expression or genetic polymorphisms have described alteration and pathogenesis of numerous diseases such as diabetic retinopathy, cancer, heart failure, cardiomyopathy or asthma." (PMID 34367381, 2021). "Higher levels of endothelin-1 have been associated with heart failure severity and higher mortality rates." (PMID 22588803, 2012). "We hypothesized that the Japan Score was more strongly associated with a heart failure-related biomarker, endothelin-1, compared with the STS Score, since the Japan Score includes a heart failure item (presence of acute heart failure within two weeks)." (PMID 40385809, 2025). "The combination of these surgical risk scores and serum endothelin-1 may improve early detection of heart failure in cardiac surgery and enable the determination of treatment strategies according to the risk of each patient." (PMID 40385809, 2025). "Based on our results, the endocan and endothelin-1 as vascular biomarkers and NT-proBNP may help to identify IgAN patients at high risk for subclinical heart failure and further atherosclerotic disease." (PMID 39408883, 2024). "In conclusion, our study confirmed that serum endocan and endothelin-1 alone and combined with NT-proBNP may help to identify IgAN patients at high risk for subclinical heart failure and further vascular disease." (PMID 39408883, 2024). "ET-1 (endothelin-1) is implicated in the pathophysiology of heart failure and renal disease." (PMID 37039015, 2023). "Elevated levels of biomarkers of systemic inflammation, immune function, and ventricular remodeling, such as C-reactive protein (CRP), tumor necrosis factor (TNF), and endothelin-1, also have been associated with morbidity and mortality among heart failure patients." (PMID 22588803, 2012). "The plasma endothelin-1 level was shown to be a promising indicator for predicting the risk of postoperative AKI and heart failure in patients undergoing cardiac surgery." (PMID 40385809, 2025). "Studies involving patients with pathological cardiac hypertrophy and heart failure have shown elevated levels of angiotensin II (Ang II), endothelin-1 (ET-1), insulin-like growth factor 1 (IGF-1), and catecholamines compared to healthy individuals." (PMID 40943251, 2025). "It is also pointed out that plasma levels of endothelin-1 have been reported to increase in heart failure due to different pathological situations." (PMID 38786079, 2024). "Endothelial cells produce endothelin, and levels of endothelin-1 (ET-1) are elevated in heart failure." (PMID 39687084, 2024). "In fact, there occurs a positive correlation between plasma levels of endothelin-1 and the degree of cardiac dysfunction in heart failure." (PMID 38786079, 2024).
heart failure (continued). "It has been reported that patients with cardiac failure display augmented plasma endothelin-1 concentrations and expression of myocardial endothelin receptors, and the degree of the elevations correlates with disease severity." (PMID 37240239, 2023). "Less is known about the potential role of endothelin-1 (ET-1) in sepsis cardiomyopathy, whereas an increase has been reported in chronic cardiac disease (i.e., heart failure)." (PMID 36139408, 2022). "Endothelin-1 (ET-1) signaling increases cell survival signaling in cardiomyocytes, which explains its activation in heart failure." (PMID 34149423, 2021). "Cardiac remodeling is an important adaptive response of cardiomyocytes to a variety of mechanical insults such as pressure overload and neurohormonal stimuli such as Ang II, endothelin-1, and adrenaline, which eventually lead to heart failure." (PMID 31231210, 2019). "Endothelin-1 is an early protective factor in heart failure in vivo and the immediate antagonism of its receptors reduces survival and worsens remodeling in the rat after PMI." (PMID 30233357, 2018). "Most studies reported that high plasma endothelin-1 (ET-1), big ET-1, and C-terminal proET-1 (CT-proET-1) were correlated with poor prognosis of heart failure (HF)." (PMID 29390406, 2017). "Endothelin‐1 (ET‐1) is a pivotal mediator of vasoconstriction and inflammation in congestive states such as heart failure (HF) and chronic kidney disease (CKD)." (PMID 28320895, 2017). "Perhaps of most significance is the ERA-resistant heart failure resulting from cardiac over expression of human EDN1 in mice, where combined ETA- and ETB-antagonist treatment failed to prevent the lethal effects of this transgenic modification." (PMID 28694457, 2017). "Increased concentrations of EDN1 are an extremely sensitive marker of heart failure severity and predict a worse prognosis." (PMID 27843475, 2016). "This is consistent with the present results and with previous results, showing enhanced pulmonary vasoreactivity to endothelin-1 in experimental heart failure." (PMID 24499246, 2014). "Both in control and cold-treated groups of broilers, endothelin 1 mRNA expression levels in lungs from ascitic chickens were higher than levels from healthy birds (P < 0.05), whereas levels in animals with cardiac failure were intermediate." (PMID 24286074, 2013). "They showed that rat heart failure, initiated by high levels of endothelin-1 (ET-1) had high levels of dihydroethidium oxidation, a measure of superoxide elevation." (PMID 24232452, 2013). "Endothelin-1 or the more stable C-Terminal portion of pro-Endothelin-1(CTproET1) has also been found to be predictive of death or heart failure following an AMI." (PMID 20529285, 2010). "However, the role of endothelin-1 (ET-1) in heart failure remains controversial due to its different receptors including ET-1 receptor type A (ETAR) and ET-1 receptor type B (ETBR)." (PMID 38166688, 2024). "Furthermore, the parallel neurohormonal dysregulation with angiotensin II, endothelin-1, and sympatho-adrenergic overactivation, which occurs in heart failure, stimulates ventricular cardiomyocyte hypertrophy and aggravates the cellular damage." (PMID 38473911, 2024). "In light of this, our team proposed that C-terminal pro-endothelin-1 (CT-proET-1) and mid-regional pro-adrenomedullin (MR-proADM) levels would be higher in heart failure patients compared to controls, and that the degree of this elevation would be related to cardiopulmonary reserve." (PMID 36264449, 2022). "Moreover, the vasoactive peptide endothelin-1 (ET-1) has been found to promote cardiac fibrosis and heart failure in diabetic hearts through stimulation of EndMT." (PMID 34205197, 2021). "EDN1 gene is a vasoconstrictor and mitogen with a role in hypertrophy and heart failure." (PMID 33233382, 2020).